TRAF3 (TNF receptor associated factor 3)
Diseases named in the same sentence as TRAF3 in open-access papers (continued):
Sharing a sentence is not in itself a finding about the gene and the disease.
infection (continued). "TRAF3 promotes IFN-I production and inhibits inflammatory cytokine production typically through modification by different types of ubiquitination in response to infection or stimulation." (PMID 40623121, 2025). "Although expression of Traf3 and Traf6 moderately suppressed infection, they did not alter the increase in IAV production from Usp25−/− cells." (PMID 37683630, 2023). "After infection, the pro-inflammatory cytokines induced by the ΔEfb stain remained higher than the Newman strain in wild-type TRAF3, but not in TRAF3 K155R-expressing macrophages." (PMID 36123338, 2022). "However, as the infection proceed, the virus induces the miR-576-3p expression promoting the down regulation of its target genes STING and TRAF3)." (PMID 29813068, 2018). "MAVS and TRAF3 did not presented a significant down-regulation at 12 h post infection; however, both presented significantly down-regulation at 24 h post infection (2 and 7.4 fold, respectively)." (PMID 29813068, 2018). "Furthermore, most of the immune-related genes, particularly TLR7, TRAF3, Mx, TRIM25, CD4, and CD8α, increased in response to GPV and H9N2 infection." (PMID 27916934, 2016). "In addition, the expression levels of TLR1, TLR2, TLR7, and TRAF3 were significantly increased in response to GPV and H9N2 infection." (PMID 27916934, 2016). "In addition, TRAF3 was significantly increased in MCC1274- and MCC12-treated PIE cells after the infection with OSU or UK RVs." (PMID 27023883, 2016). "Western blotting indicated that the TRAF3 mutation did not influence insulin signalling and TAK1–JNK/NF-κB pathways, unlike in TRAF3 (WT)-treated cells, and had a comparable effect on these molecular events to AdGFP infection." (PMID 26882989, 2016). "Confocal microscopy experiments revealed that addition of dilysine and dihydrophobic residues to the C-terminal end of TRAF3 resulted in the formation of large TRAF3 aggregates which failed to colocalize with the Golgi marker GM130 upon infection with SeV." (PMID 22792062, 2012). "Both MAVS and TRAF3, but not RIG-I, associate with PKR in a time dependent manner, beginning at 2 hrs post-infection." (PMID 22022264, 2011). "TRAF3−/− MEF showed a significant reduction of IFN-β mRNA levels at 24 hours and 48 hours post infection (7.8-fold, P<0.0001 and 2.4-fold, P<0.05, respectively), which was confirmed by measuring IFN-β in the cell supernatant (3.7- and 1.4-fold decrease, respectively, P<0.0001)." (PMID 19798431, 2009). "However, upon infection with SE, we found 11 of the TLR reference genes that were significantly up-regulated in heterophils from line A when compared to line B (MD-2, TIRAP, IRAK4, TRAF3, TAK1, IKKε, IKKα, NF-κB2, PI-3K, p38, and IRF7)." (PMID 22783275, 2012). "Infection with RNA viruses or transient transfection with dsRNA can directly and rapidly induce early ISGs, such as ISG15, through IRF3, after activation of the RIG-I/MAVS pathway and recruitment of TRAF3, an essential adapter which recruits the downstream IRF3 kinases TBK1/IKKε." (PMID 22022264, 2011). "Interestingly, upon SeV infection or stimulation with Poly(I:C), TRAF3 recruitment to TFG-containing immunocomplexes was further increased compared to that in control cells, plateauing at 4h for poly(I:C) transfection and increasing between 8 to 24 h post infection with SeV." (PMID 33411856, 2021). "TRAF3, NEMO and TBK1 are cytosolic proteins, and their respective amounts remained unaffected by the infection in the presence or the absence of MG132." (PMID 22626058, 2012). "Surprisingly, TRAF3 deletion in myeloid cells did not sensitize mice to VSV infection, since the Traf3MKO and wild-type control mice displayed comparable survival rate following intravenous (i.v.)infection with VSV." (PMID 30622699, 2019).
bacterial infection (6 papers, 2014 to 2025). "We previously reported defective TCR signaling and considerably impaired T cell responses to immunization and bacterial infection in mice with loss of TRAF3 specifically in T cells." (PMID 25010048, 2014). "The different detailed mechanisms by which Triad3A regulates TRAF3 ubiquitination with different domains remain to be clarified in the state of endotoxin tolerance and bacterial infection." (PMID 37506157, 2023). "Recently, HECTD3 is implicated as an E3 ubiquitin ligase for TRAF3 and STAT1 in bacterial infection, hypothermic oxygenated perfusion of liver and cardiac inflammation models." (PMID 37402711, 2023). "Specifically, TLR9 constitutively associates with Cav-1 and facilitates MyD88-mediated TRAF3 and IRF3 signal transduction, providing the observed InP effect in fatal doses of bacterial infection." (PMID 31534550, 2019). "HECTD3 has been reported to mediate the innate immune response to bacterial infection via promoting the ubiquitination of TRAF3, therefore one obvious question is whether TRAF3 is also the substrate of HECTD3 that mediates the anti-RNA virus response." (PMID 37402711, 2023). "We hypothesized that Triad3A or TRAF3 could play a role in controlling the bacterial infection through the TLR‐NO pathway, thus we detected the expression of Triad3A and TRAF3, and the change of signal pathway caused by Triad3A in cells infected with M. marinum." (PMID 37506157, 2023).
inflammation (2 papers, 2021 to 2025). Aberrant reaction of the microcirculation characterized by movement of fluid and leukocytes from the blood into extravascular tissues. "Taken together, these data suggest that upregulated miR-153 induced by HTG aggravates pancreatic inflammation and delays repair likely via suppressing TRAF3." (PMID 33491670, 2021).
brain conditions (1 paper, 2021). "Further, the NR-Traf3 mouse provides a tool for investigations of neuronal TRAF3 as a novel potential target for therapeutic interventions aimed at suppressing retinal inflammatory disease and may also inform treatment approaches for inflammatory neurodegenerative brain conditions." (PMID 34440839, 2021).
heart disease (1 paper, 2024). "As TNF-α is cardiotoxic and can induce cardiac dysfunction, and production of TNF-α by transgenic cardiomyocytes was sufficient to cause severe heart disease, we hypothesized that ADAM17 may upregulate TRAF3 expression through TNF-α." (PMID 39406701, 2024).
liver (1 paper, 2021). "Particularly, upon DCD liver IR insult, the DOC and HECT domains of HECTD3 directly bind to TRAF3, and the C832 of the HECT domain promotes the K63-linked polyubiquitination of TRAF3 at Lys138 to trigger oxidative stress and inflammatory response, thereby leading to serious liver IRI." (PMID 33627626, 2021). "Further, western blot results showed that the expression levels of HECTD3 and TRAF3 in the IR group were significantly higher than those in the control group, suggesting that human liver IR during DCD liver transplantation promotes the expression of HECTD3 and TRAF3." (PMID 33627626, 2021).
TRAF3 also shares sentences with these, for which no sentence is quoted: B-cell chronic lymphocytic leukemia (5 papers); Hodgkins lymphoma (4); metabolic disease (4); Immunodeficiency (3); marginal zone lymphoma (3); systemic lupus erythematosus (3); eczema (2); myeloid malignancies (2); neurodegenerative disease (2); non-alcoholic fatty liver disease (2); psoriasis (2); Waldenström’s macroglobulinemia (2); acute myocardial infarction (1); allergic asthma (1); allergic rhinitis (1); anemia (1); antibody deficiency (1); arteriosclerosis (1); autoimmune hemolytic anemia (1); biliary tract cancer (1); bladder carcinoma (1); Burkitt lymphoma (1); cardiovascular diseases (1); cerebral infarct (1); cervical neoplasm (1); Cholecystitis (1); coronary heart disease (1); degenerative arthritis (1); dermatitis (1); dilated cardiomyopathy (1).
A further 37 diseases each share a sentence with TRAF3 in 1 paper.